BCL2 (BCL2 apoptosis regulator)
Diseases named in the same sentence as BCL2 in open-access papers (continued):
Sharing a sentence is not in itself a finding about the gene and the disease.
bladder cancer (continued). "However, silencing of PLCɛ was suggested to induce apoptosis via modulation of bcl-2 and bax in bladder cancer and recent literature data suggest that PLC ε might bear cancer-suppression activity." (PMID 27026853, 2016). "Reversing the ratio of Bcl2/Bax might affect the bladder cancer cells." (PMID 26743236, 2016). "Overexpression of XIAP and BCL2 inhibits the apoptosis of cancer cells, and XIAP also enhances human invasive bladder cancer cell proliferation." (PMID 36430344, 2022). "Baicalein induces apoptosis by activating apoptosis-related genes, including Bcl2, Bcl-xL, and XIAP, with effects on both their mRNA and protein levels in T24 and 253J bladder cancer cells." (PMID 33996570, 2021). "In this study, we report that BA inhibits bladder cancer cell progression and activates apoptosis by upregulating cleaved caspase 3, Bax, and cleaved PARP and by downregulating the anti-apoptotic factor Bcl-2." (PMID 34510030, 2021). "The present data demonstrate the involvement of both intrinsic and extrinsic caspase pathways of apoptosis, which were associated with PARP-1 cleavage, Bax, and Fas induction, and Bcl-2 and XIAP suppression in a MSSV-treated bladder cancer cells." (PMID 33430488, 2021). "The results of cell viability assay and immunoblot analysis as well as histone-complexed DNA fragments detection data revealed that MSSV treatment decreased the expression of Bcl-2 and XIAP in bladder cancer cells." (PMID 33430488, 2021). "In bladder cancer cells, RES also induces apoptosis by down-regulating the expression of Bcl2 proteins." (PMID 28157696, 2017). "Since Bcl-2 was the target of AKT signaling pathway, we checked the change of AKT activity and found that Derlin-1 positively modulate AKT phosphorylation in bladder cancer cells." (PMID 28178653, 2017). "Taken together, all these findings substantiated that JNK and ERK activation are involved in GEM-stimulated Bcl-2 phosphorylation and inhibition of JNK and ERK potentiates GEM-induced apoptotic cytotoxicity in bladder cancer cells." (PMID 29069735, 2017). "In conclusion, our study demonstrated that Derlin-1 is overexpressed in bladder cancer and promotes malignant phenotype through ERK/MMP and PI3K/AKT/Bcl-2 signaling pathway." (PMID 28178653, 2017). "As far as we known, the caspases, Bcl-2, Bcl-xL and PARP were related to cell apoptosis in bladder cancer." (PMID 28088793, 2017). "Moreover, Bcl2 and Bcl-XL, as pro-survival genes directly transcripted by STAT3, were also repressed by metformin, suggesting that down-regulaiton of STAT3/Bcl2/Bcl-XL signaling pathways in metformin-treated bladder cancer cells caused increased apoptotic cell death." (PMID 26245871, 2015). "For instance, AITC induces cell cycle arrest at G2/M phase and apoptosis in human bladder cancer cells and inhibits tumor growth of bladder cancer cell xenograft via JNK activation and Bcl-2 phosphorylation." (PMID 23895248, 2013). "Accordingly, bcl-2 proved to be a useful discriminatory factor between SBT and NSBT, cystitis and bladder cancer, and cancer/cystitis and CTL." (PMID 19243595, 2009). "Furthermore, SFN induces apoptosis in cancer cells by increasing mitochondrial permeability, releasing cytochrome C, and modulating proteins like Bcl-2 and caspases, with ROS-dependent pathways activating caspases and cleaving PARP in bladder cancer cells." (PMID 40597933, 2025). "In the T24 bladder cancer cell line, THP treatment significantly increased the expression of apoptosis-related proteins, such as BAX, cleaved caspase-3, caspase-8, and caspase-9, while the expression level of anti-apoptotic protein BCL-2 was inhibited." (PMID 37173953, 2023).
bladder cancer (continued). "Recently, the research revealed that BMSCs-derived exosomal miR-19b-1-5p could inhibit bladder cancer cell lines (T24, UC3, 5637, and J82) from migrating, proliferating, or invading while promoting cell death via inhibiting ABL2, Bcl-2, MMP2 and MMP9." (PMID 36684446, 2022). "In bladder cancer, CCR7 enhanced pro-survival Bcl-2, while decreasing pro-apoptotic Bax proteins." (PMID 35203305, 2022). "Moreover, treatment with 9-ING-41 led to a decreased expression of antiapoptotic molecules, Bcl-2 and XIAP, resulted in an increased apoptosis as shown by PARP cleavage in bladder cancer cells." (PMID 31882719, 2019). "Bcl-2 was shown to phosphorylate without the expression alteration of Bax levels in human bladder cancer cells, which is similar to our study that Bax level was not changed by BITC." (PMID 31817791, 2019). "After transfection with artificial hTERT promoter-Bax-Anti Bcl2 combination module or negative control, bladder cancer 5637 cells, T24 cells and NHF were analyzed by the cell proliferation assay with CCK-8 and MTT." (PMID 26743236, 2016). "The cell proliferation inhibition and apoptosis induction were observed in artificial hTERT promoter- Bax-Anti Bcl2 combination module -transfected bladder cancer 5637 and T24 cells, but not in the module -transfected normal human fibroblasts." (PMID 26743236, 2016). "qRT-PCR analysis found the expression of NF-κB-targeted genes, including CCND1, Bcl-2, MMP9 and VEGF were upregulated once overexpression of URGCP/URG4, whereas knockdown of URGCP/URG4 significantly inhibited the levels of these genes in bladder cancer cells." (PMID 26429874, 2015). "However, the results of the present study reveal a positive correlation between the expression levels of BCL2 and BAX genes in bladder cancer." (PMID 25295115, 2014). "The role of the Bcl-2 and the IAP family proteins was determined by Western blotting to investigate which mechanisms were involved in the sanguinarine-induced apoptosis in the bladder cancer cells." (PMID 23717422, 2013). "We believe that analysis of molecular markers such as BAX, BCL2, CD40 and CD40L may prove valuable in identifying patients with poor prognosis bladder cancers who may benefit from aggressive treatment and this should be considered in future trial design." (PMID 12592374, 2003). "Therefore, the aim of this study was to determine whether concentrations of heavy metals such as Pb, Cr, Hg, and Cd have any effect on oxidative stress and expression of some genes Bcl-2, Bax, IL-6, AKT, and P38 genes in bladder cancer patients." (PMID 38072891, 2024). "Results showed that deletion of PRC1 inhibited bladder cancer cells’ ability to proliferate and spread, as well as halted the induction of EMT, which was shown by changes in the production of E-cadherin, and Bax and decreases in the synthesis of N-cadherin, Vimentin, SNAIL, Bcl-2, and PCNA." (PMID 36684446, 2022). "As with BCL-2 and MCL-1, for which deregulation of the microRNA control of their expression has been described in cancer, miR-133b deregulation has been observed in bladder cancer, colorectal carcinoma and lung cancer leading to BCL-W overexpression in these cancers." (PMID 33799592, 2021). "However, it should be noted that the role of BCL-2 expression as a prognostic marker also does not always hold up such as in studies of advanced head and neck carcinoma and bladder cancer." (PMID 33799592, 2021). "However, resistance to EPI becomes a great challenge in treating bladder cancer because it induces cytoprotective autophagy in bladder cancer cell lines T24 and BIU87 via the activation of JNK-mediated phosphorylation of Bcl-2 and disruption of the Bcl-2/Beclin1 complex." (PMID 34575981, 2021).
bladder cancer (continued). "They did not assess Bcl-2 or Bcl-xL expression levels; however, their data are compelling and further support the use of Obatoclax to abrogate pro-survival Bcl-2 family member-mediated intrinsic chemoresistance in bladder cancers." (PMID 30875757, 2019). "According to these findings, when exposed to a higher dose of cisplatin (10 μg/ml), bladder cancer cell lines with high TACC3 or E2F1 expression were both characterized by a strong transactivation response by Bik and Bim, which paralleled a severe downregulation of the Bcl-2 gene." (PMID 29358577, 2018). "Furthermore, we identified a novel pathway consists of HMGB1, ERK, JNK and Bcl-2 for GEM-induced cytoprotective autophagy, and intervention targeting this pathway may improve the anticancer activity of GEM against bladder cancer." (PMID 29069735, 2017). "To analyze samples negative for BCL2 methylation, we expanded the MethyLight-based analysis by six additional promoter CpG islands previously reported to be frequently hypermethylated in bladder cancer, including CCNA1, EOMES, HOXA9, POU4F2, SALL3 and VIM2." (PMID 24732047, 2014). "However, in the present study, there was no change in the expression of Bcl-2 and c-myc proteins, contrary to previous reports in bladder cancer cells." (PMID 23762338, 2013). "Therefore, simultaneous knockdown of antiapoptotic BCL2, Bcl-xL, XIAP and survivin may represent a promising treatment option for bladder cancer." (PMID 22797576, 2012). "Level of Pb, Cr, Hg and Cd, oxidative stress markers, and gene expression of Bcl-2, Bax, IL-6, AKT, and P38 genes were detected in cancer and non-cancerous tissues obtained from bladder cancer patients." (PMID 38072891, 2024). "The anti-apoptotic protein Bcl-2, on the other hand, was not detectable in the mitochondrial fraction of TTC, but could be seen in bladder cancer cells." (PMID 37891379, 2024).
Cerebral ischemia (131 papers, 2009 to 2026). Restriction of arterial blood supply to the brain associated with insufficient oxygenation to support the metabolic requirements of the tissue. "Apoptosis induced by cerebral ischemia leads to changes in the ratio of Bcl-2 to Bax, so Bax and Bcl-2 are common genes associated with the mechanism of apoptosis." (PMID 35721195, 2022). "Lutein prevents loss of Bcl-2 and Bcl-xL, accumulation of Bax, and activation of caspases 3 and 8 in brain disease models of cerebral ischemia and Parkinson’s disease." (PMID 32751250, 2020). "In the present study, cerebral ischemia/reperfusion caused an increase in the protein expression of Bax and c-Jun, as well as a reduction in Bcl-2 expression in the hippocampus." (PMID 26094797, 2015). "Similarly to Dexmedetomidine, Propofol increased Bcl2 and decreased Bcl2-associated protein three days after cerebral ischemia and reperfusion in the hippocampus." (PMID 36139756, 2022). "THg alleviates brain edema after cerebral ischemia by inhibiting thrombus formation, promoting Bcl-2 expression, and suppressing Bax expression in brain tissue, thereby enhancing brain cell tolerance to ischemia and hypoxia and facilitating brain repair." (PMID 40191596, 2025). "Further, animal models overexpressing HO-1 in neurons show higher protection after cerebral ischemia by mechanisms lowering lipid peroxidation and upregulating the Bcl-2 anti-apoptotic protein." (PMID 38672695, 2024). "Accumulating evidence indicates that a set of proteins from the B-cell lymphoma (Bcl-2) family plays a significant role in governing neuronal death during cerebral ischemia." (PMID 39159207, 2024). "Our study found that iTBS was able to down-regulate the level of CHOP and up-regulate the level of Bcl-2, attenuating neuronal apoptosis in rats after cerebral ischemia-reperfusion." (PMID 38427114, 2024). "Activation of the PI3K/Akt signaling pathway was reported to reduce apoptosis by enhancing Bcl-2 expression in brain ischemia–reperfusion injury." (PMID 39594481, 2024). "It has been reported that down regulation of caspase-3 expression and up regulation of Bcl-2 expression can both inhibit neuronal apoptosis produced by cerebral ischemia." (PMID 36449200, 2023). "The suppression of CREB pathway inhibited the expression of BDNF and Bcl-2, which affected neuronal survival after cerebral ischemia." (PMID 37153779, 2023). "SA increases the expression of apoptosis-related protein Bcl-2 and decrease the expression of Bax in cerebral ischemia-reperfusion injury." (PMID 36778008, 2023). "Accumulating evidence suggests that a group of proteins of the B‐cell lymphoma (Bcl‐2) family are profoundly involved in the regulation of neuronal death in cerebral ischemia." (PMID 37750289, 2023). "Crocin inhibits the Bax/Bcl-2 ratio in endogenous NSCs, reduces inflammatory factor release, and enhances Notch1 expression after cerebral ischemia reperfusion in the rat brain." (PMID 37242489, 2023). "m6A demethylases Alkbh5/Fto protect neurons from damage after cerebral ischemia–reperfusion injury by selectively demethylating the Bcl2 mRNA, preventing Bcl2 mRNA degradation and thus enhancing Bcl2 translation." (PMID 37612540, 2023). "Several studies have shown that intracerebroventricular injection of insulin after whole brain ischemia upregulates Bcl-2 and Bcl-x protein expression in the hippocampal CA1 region and reduces neuronal apoptosis." (PMID 37256231, 2023). "For the validation of neuronal apoptosis, the expression of Bax and Bcl-2 in different treatment groups was examined at 24 h after cerebral ischemia by Western blot analysis." (PMID 36077582, 2022). "The present study demonstrates that βCAR exhibits neuroprotective effects on cerebral ischemia by modulating the expression of Bax and Bcl2 proteins." (PMID 36552554, 2022).
Cerebral ischemia (continued). "Bcl-2 has been widely studied in various models of cerebral ischemia where it exerts neuroprotection, and bcl-2 deficient mice display prominent infarct volumes and an aggravated neurological deficit compared to wild type mice." (PMID 34483846, 2021). "The Bcl-2 protein family is also involved in the process of apoptosis after cerebral ischemia, and there is a decrease in the antiapoptotic protein Bcl-2 and an increase in the proapoptotic protein Bax." (PMID 34733340, 2021). "It is reported that the overexpression of Bcl-2 presents neuroprotective effect against nerve cell apoptosis in rats following cerebral ischemia." (PMID 33815123, 2021). "As a matter of fact, ectopic delivery or overexpression of bcl-2 induces neuroprotection against cerebral ischemia." (PMID 34483846, 2021). "Intriguingly, it has been reported that interaction of mitochondrial Rac1 with Bcl-2 is implicated in generation of ROS, in which inhibition of formation of Rac1/Bcl-2 ameliorates neuronal oxidative stress damage following cerebral ischemia reperfusion." (PMID 34658788, 2021). "The one control patient had died of cardiac arrest and was likely to have experienced cerebral ischemia as a reason for Bcl-2 upregulation." (PMID 32570722, 2020). "Bax/Bcl-2 regulates mitochondrial membrane permeabilization and cerebral ischemia will increase Bax/Bcl-2 ratio thus promote apoptotic neuronal death by facilitating Cyt C release and caspase-3 activation." (PMID 32848589, 2020). "Ellagic acid protected against ischemic injury in both cellular and in vivo models of brain ischemia by regulating Bcl-2/Bax expression." (PMID 33383852, 2020). "To investigate the role of SENP1 on cell apoptosis, we focus on the expression of the apoptosis‐related proteins, such as Fas‐L, bcl‐2, and cleaved caspase 3 during brain ischemia." (PMID 32495523, 2020). "To this end, we used a retroviral delivery system encoding the transcription factor Ngn2 alone or in combination with the antiapoptotic factor Bcl-2 to target proliferating astrocytes in the neocortex of young and aged mice after cerebral ischemia." (PMID 31849638, 2019). "On the one hand, tetrahydropalmatine reduces the apoptosis through enhancing the expression of Bcl-2 and reducing Bax/Bcl-2 ratio in cerebral ischemia-reperfusion and endothelial cells against γ-irradiation injury." (PMID 31781263, 2019). "In this work, we used a retroviral delivery system encoding the transcription factor Ngn2 alone or in combination with the anti-apoptotic factor Bcl-2 to target proliferating astrocytes in the neocortex of young and aged mice after cerebral ischemia." (PMID 31849638, 2019). "During cerebral ischemia, p-p90RSK phosphorylates the pro-apoptotic protein Bad and p-Bad subsequently prevents Bad interaction with Bcl-2 and inhibits pro-apoptotic protein Bax translocation to the mitochondria in the ischemic brain." (PMID 31655619, 2019). "The cerebral ischemia decreased the percentage of Bcl-2-positive cells (21.4%±1.55) compared to the sham group (P<0.001)." (PMID 32284834, 2019). "The expression of anti-apoptotic protein Bcl-2 in rats subjected to cerebral ischemia was markedly increased by implantation of APSCs." (PMID 31588228, 2019). "Bcl-2 has long been shown to confer protection against a variety of neurological insults including oxidative stress, excitotoxicity, and cerebral ischemia." (PMID 30594149, 2018). "17β-estradiol alone or in combination with progesterone was found to upregulate miR-375 expression and its target BCL2 in rat model of cerebral ischemia." (PMID 29137141, 2017). "The animal studies of brain ischemia-reperfusion injury showed that the level of Bcl-2 was more decreased in severe brain injury." (PMID 28147324, 2017). "The dynamic balance between antiapoptotic Bcl-2 (Bcl-xL) and proapoptotic Bax proteins plays a key role in determining cell fate during cerebral ischemia." (PMID 27187745, 2016).